ENSG00000221398
Synonyms: LOC124900475
Gene: Small nucleolar RNA gene on chromosome 21 (34,456,110 to 34,456,237, reverse strand). Ensembl gene ENSG00000221398.
Gene Ontology:
Biological process: RNA processing
Cellular component: nucleolus
Homologues: Orthologues: mouse Gm22488 (72% identical), rat LOC120100477 (69% identical), rat Snora11g (69% identical). Paralogues in human: SNORA11D (82% identical), SNORA11E (82% identical), SNORA11F (82% identical), SNORA11B (78% identical), SNORA11C (78% identical), SNORA11 (77% identical), SNORA11G (72% identical).